GPR174 (G protein-coupled receptor 174)
Diseases named in the same sentence as GPR174 in open-access papers:
GPR174 is named in the same sentence as 21 diseases in open-access papers, as found by Europe PMC text mining. Sharing a sentence is not in itself a finding about the gene and the disease. The quoted sentences say what the papers report.
Graves disease (5 papers, 2019 to 2022). Graves' disease is an autoimmune disorder that leads to overactivity of the thyroid gland (hyperthyroidism).It is caused by an abnormal immune system response that causes the thyroid gland to produce too much thyroid hormones. "The GPR174 gene is located on X chromosome, which is associated with autoimmune thyroid disease, including Graves’ disease." (PMID 30616589, 2019). "Recently, GPR174, a seven-transmembrane G protein-coupled receptor, was identified to be mainly expressed on immune cells such as T/B cells and reported as a risk factor for subcutaneous metastases, Graves’ disease, and autoimmune Addison’s disease." (PMID 35173706, 2021).
Sepsis (5 papers, 2019 to 2022). Sepsis is defined as life-threatening organ dysfunction caused by a dysregulated host response to infection. "In Gpr174-KO mice induced by LPS or CLP to simulate sepsis, the induction of M2 macrophages in the early stage was Treg dependent and Gpr174-deficient Tregs protected mice from sepsis-induced ALI and improved survival by promoting M2 macrophage polarization." (PMID 35281010, 2022). "The suppressive role of Tregs in the sepsis-induced immune-inflammation/cytokine storm was also demonstrated in a study using G protein-coupled receptor 174 (GPR174)-deficient mice." (PMID 35370925, 2022). "In conclusion, our results first showed that the expression of GPR174 mRNA is associated with disease severity and mortality in sepsis." (PMID 35173706, 2021). "All these results suggested that decreasing GPR174 mRNA was associated with increased mortality in sepsis." (PMID 35173706, 2021). "The major finding of this study was that Gpr174-deficient Treg cells controlled and down regulated the pro-inflammatory cytokines in LPS-induced sepsis, and thus leaded to dramatical attenuation of LPS-induced tissue injury." (PMID 30850582, 2019). "Taken together, these results suggested that Gpr174-deficient Treg cells alleviated lung injury by attenuating pro-inflammatory response in sepsis." (PMID 30850582, 2019). "Meanwhile, depletion of Treg cells in WT and Gpr174-deficient mice resulted in low levels of IL-10, which plays an important role in attenuating sepsis induced tissue damage." (PMID 30850582, 2019). "Gpr174-deficient Treg cells controlled macrophage polarization via IL-10 dependent and cell-cell contact dependent pathway in LPS-induced sepsis." (PMID 30850582, 2019). "The protective function of Gpr174-deficient Treg cells was associated with a striking increased of M2 macrophages in sepsis." (PMID 30850582, 2019). "GPR174, a member of the G-protein-coupled receptor family, plays a negative role in the development and functionality of Tregs which is highly expressed on the surface of Tregs in the early stages of sepsis and closely associated with adverse sepsis outcomes." (PMID 35281010, 2022). "In summary, our results indicated that the expressions of GPR174 mRNA were associated with the severity of sepsis, suggesting that GPR174 could be a potential prognosis biomarker for sepsis." (PMID 35173706, 2021). "In the current study, using Gpr174-deficient mice, we demonstrated that GPR174 could strengthen LPS-induced tissue injury by amplifying cytokine storm in the initial phase of sepsis." (PMID 30850582, 2019). "By using the LPS-induced sepsis model, we demonstrated that anti-inflammatory macrophages (M2 macrophages) induction was Treg cell-dependent and Gpr174-deficient Treg cells protected mice against sepsis-induced lung damage through prompting M2 macrophages polarization." (PMID 30850582, 2019). "Then, we explored whether Gpr174-deficient Treg cells affected the polarization of macrophages in the process of sepsis." (PMID 30850582, 2019). "In this study, we investigated the role of GPR174 in regulating suppressive function of regulatory T cells (Treg cells) and the underlying mechanism of Gpr174-deficient Treg cells in controlling cytokine storm of sepsis." (PMID 30850582, 2019). "So in our LPS-induced sepsis, tolerance to LPS was associated with Gpr174-deficient Treg cells." (PMID 30850582, 2019). "In our study, IL-10 was similar between wild-type and GPR174-deficient Tregs after hindlimb ischemia, the difference might possibly be related to the degree of inflammation response, in that inflammation response is overwhelming in sepsis model, while ischemia is dominant in our HLI model." (PMID 36473866, 2022). "Then, the clinical values of GPR174 for the diagnosis, severity assessment, and prognosis of sepsis were analyzed." (PMID 35173706, 2021).
Sepsis (continued). "This study is aimed to evaluate the potential value of GPR174 as a prognostic biomarker for sepsis and explore the pathological function of GPR174 in cecal ligation and puncture (CLP)-induced septic mice." (PMID 35173706, 2021). "Further studies are needed to explore the regulating mechanism of GPR174 on immune cells during sepsis." (PMID 35173706, 2021). "Second, further studies are needed to explore the exact function and mechanism of GPR174 in the host immune response during sepsis." (PMID 35173706, 2021). "Taken together, these results suggested that GPR174 affects the sepsis pathogenesis via regulation of Treg cells suppressive functions." (PMID 30850582, 2019). "To explore the function of GPR174 in the development of sepsis, we generated a mouse model with global-targeted deletion of Gpr174." (PMID 30850582, 2019). "In conclusion, these findings suggested that GPR174 plays an important role in the initial period of sepsis through the regulation of macrophage polarization and pro- and anti-inflammatory cytokine secretions." (PMID 30850582, 2019). "The levels of GPR174 mRNA at Day 7 had a high AUC in predicting the death of sepsis (0.83)." (PMID 35173706, 2021). "We further investigated the prognostic value of GPR174 mRNA in sepsis with the ROC analysis." (PMID 35173706, 2021). "Then, RNA-seq was used to explore the mechanism of GPR174 in the pathogenesis of sepsis." (PMID 35173706, 2021). "To explore the effects of GPR174 in sepsis, we conducted a series of animal studies and found that GPR174 could regulate the anti-inflammatory response by negatively regulating Treg and B cell functions and attenuating the tissue injury." (PMID 35173706, 2021). "Interestingly, with the recovery of sepsis, the concentration of GPR174 mRNA in septic patients returned to the level of healthy subjects." (PMID 35173706, 2021). "Moreover, decreased relative expression of serum GPR174 mRNA was related to the illness severity of sepsis." (PMID 35173706, 2021). "However, the clinical values of GPR174 for the diagnosis, severity, and prognosis of sepsis have yet to be investigated." (PMID 35173706, 2021). "Previous studies indicated that G-protein coupled receptor 174 (GPR174) is involved in the dysregulated immune response of sepsis, however, the clinical value and effects of GPR174 in septic patients are still unknown." (PMID 35173706, 2021). "In addition, GPR174 plays an important role in the development of sepsis by regulating the inflammatory response." (PMID 35173706, 2021). "To determine whether GPR174 plays a role in the pathogenesis of sepsis, we produced LPS-induced endotoxic shock model using Gpr174 KO and WT mice respectively (n = 20 per group), and monitored survivals for 48 h." (PMID 30850582, 2019). "Furthermore, we found that depletion of Gpr174 alleviated the tissue damage and promoted the polarization of macrophages toward M2-like cells induced by sepsis via Treg cells." (PMID 30850582, 2019). "Our data also found that GPR174 regulated the function of Treg cells involved in the pro- and anti-inflammatory cytokine secretions during sepsis and highlighted GPR174 as a potential therapeutic target for clinical intervention to manage sepsis." (PMID 30850582, 2019). "In the present study, we investigated whether GPR174 played a role in the process of sepsis via regulation of Treg cells function." (PMID 30850582, 2019). "Other studies have revealed that GPR174-deficient Tregs are associated with the reduced severity of autoimmune encephalomyelitis and sepsis-induced lung injury, which may be attributed to the fact that GPR174 is a negative regulator of Treg proliferation and function." (PMID 36473866, 2022). "However, the role of GPR174 in the immune response of sepsis is unclear." (PMID 30850582, 2019). "However, the function of GPR174 in regulating inflammatory responses against bacterial infection in sepsis remains unclear." (PMID 30850582, 2019).
Sepsis (continued). "Using binary logistic regression analysis adjusted by age and gender, both GPR174 mRNA (OR = 0.004, P = 0.003) and CRP (OR = 1.010, P = 0.031) at D7 were found to be independent predictors of 90-day mortality in patients with sepsis." (PMID 35173706, 2021). "In this prospective observational study, we found that the relative expression of GPR174 mRNA was significantly lower in septic patients than that in non-septic ICU controls and healthy volunteers at D1, which indicated that GPR174 might be a novel biomarker for early diagnosis of sepsis." (PMID 35173706, 2021). "Interestingly, only GPR174 mRNA showed remarkable differences both in the non-survivor and survivor groups (ascending in the survivors and descending in non-survivors, respectively), which indicated that GPR174 might be a sensitivity prognostic biomarker in sepsis." (PMID 35173706, 2021).
autoimmune disease (4 papers, 2019 to 2022). A disorder resulting from loss of function or tissue destruction of an organ or multiple organs, arising from humoral or cellular immune responses of the individual to their own tissue constituents. "Several genome-wide association studies (GWAS) have linked GPR174-associated single-nucleotide polymorphisms (SNPs) to autoimmune disorders including Graves’ and Addison’s diseases (4, –6)." (PMID 35639700, 2022). "SNPs in GPR174 are associated in several GWAS with autoimmune disease (4, –6), and NUR77 plays a role in the pruning of peripheral autoreactive B cells in a mouse model of lupus." (PMID 35639700, 2022). "Genetic variation in GPR174 is associated with susceptibility to autoimmune disease, and GPR174-deficient mice were resistant to lipopolysaccharide-induced cytokine storm." (PMID 35715807, 2022). "G protein-coupled receptor 174 (GPR174) is mainly expressed in thymus, spleen, lymph nodes, and leukocytes, and genetic variation in GPR174 is associated with susceptibility to autoimmune diseases, indicating that GPR174 is involved in the immune response." (PMID 30850582, 2019). "Given the coincidence of GPR174 expression in B cell development with the pruning of dsDNA-autoreactive B cells and a potential role of this receptor in human autoimmune disease, we asked whether loss of GPR174 influenced tolerance in this model." (PMID 35639700, 2022). "Variants in the GPR174 locus have been associated with autoimmune diseases." (PMID 35639700, 2022). "Altered activity of the GPR174 signaling pathway in B cells may contribute to development of Graves’, Addison’s, and possibly other autoimmune diseases." (PMID 35639700, 2022).
colitis (2 papers, 2022). Inflammation of the colon. "Our study showed that Gpr174 knockout reduced inflammatory response and altered the phenotype of DCs in colitis intestines." (PMID 35669778, 2022). "After oral administration of DSS for 7 days and 2 days on regular drinking water, Gpr174 -/- mice showed improved acute colitis symptoms compared with WT mice." (PMID 35669778, 2022). "We observed lower Gpr174 expression in colonic Treg cells, and P2ry10 and P2ry10b deficiency in CD4+ T cells prevents LysoPS-dependent colitis exacerbation." (PMID 35608941, 2022). "DCs, a bridge between innate and acquired immune systems, maintain the homeostasis of intestinal immunity in the LP, were found to decrease colitis after Gpr174 knockout in this study." (PMID 35669778, 2022). "Adoptive transfer of Gpr174-/- BMDCs to WT mice ameliorated DSS-induced colitis." (PMID 35669778, 2022). "Moreover, we adoptively transferred Gpr174-/- BMDCs to alleviate DSS-induced colitis and gut injury." (PMID 35669778, 2022). "The present study aimed to identify GPR174 involved in colitis by both in vivo and vitro studies." (PMID 35669778, 2022). "In this study, we found that deletion of Gpr174 could generally alleviate intestinal injury in the DSS-induced colitis, which considered Gpr174 participated in the pathogenesis of IBD." (PMID 35669778, 2022). "Therefore, in the early course of LPS stimulation and colitis, the GPR174 might increase, while in the late course of the disease, the GPR174 expression decreased." (PMID 35669778, 2022). "In addition, we focused on the relationship between GPR174 and DCs function, which may play a critical role in regulating the intestinal injury of colitis." (PMID 35669778, 2022). "In this study, we showed that expression of Gpr174 mRNA in colonic Treg cells was low and that LysoPS did not have any effect on the Treg cell-mediated suppression of colitis." (PMID 35608941, 2022). "To further validate whether Gpr174-/- BMDCs have protective effects on IBD, we transferred Gpr174-/- BMDCs into DSS-induced colitis animals." (PMID 35669778, 2022). "However, the role of GPR174 in regulating the immune function of DC in colitis has not been investigated." (PMID 35669778, 2022). "In summary, our work revealed that the knockout of GPR174 could reduce intestinal inflammation and repair the epithelium barrier by suppressing DCs maturation and naïve T cell differentiation to alleviate DSS-induced colitis, which was probably through inhibiting the TNF-α (NF-κB) pathway." (PMID 35669778, 2022).
Autoimmunity (1 paper, 2024). The occurrence of an immune reaction against the organism's own cells or tissues. "A large effect size is associated with GPR174, G protein-coupled receptor 174, a ChrX gene that plays a role in autoimmunity pathogenesis." (PMID 38919955, 2024).
colorectal cancer (1 paper, 2021). A primary or metastatic malignant neoplasm that affects the colon or rectum. "For example, lyso-PS can provoke eosinophil degranulation via P2Y10, suppress IL-2 production by activated T cells via GPR174, and stimulate chemotactic migration and invasion of colorectal cancer cells via GPR34." (PMID 33875796, 2021).
ischemia (1 paper, 2022). A hypoperfusion of the BLOOD through an organ or tissue caused by a PATHOLOGIC CONSTRICTION or obstruction of its BLOOD VESSELS, or an absence of BLOOD CIRCULATION. "Using adaptive transfer experiment, we also showed that GPR174-deficient Tregs exerted protective effects in muscle tissues after ischemia." (PMID 36473866, 2022). "In the present study, we investigate the role of GPR174 in blood flow recovery using a hindlimb ischemia (HLI) mouse model." (PMID 36473866, 2022). "Gpr174 is a regulator of regulatory T cells, which play an important role in angiogenesis after hindlimb ischemia." (PMID 36473866, 2022).
melanoma (1 paper, 2023). A malignant, usually aggressive tumor composed of atypical, neoplastic melanocytes. "GPR174 is strongly expressed in melanoma cells, and although insulin increased GPR174 expression, it did not play a role in regulating cell proliferation." (PMID 37761999, 2023).
metastatic melanoma (1 paper, 2013). A melanoma that has spread from its primary site to another anatomic site. "Upregulated GPCR, GPR174, is an orphan receptor that is overexpressed in metastatic melanoma and contributes to tumor cell survival." (PMID 23383159, 2013).
tumor (3 papers, 2013 to 2025). "GPR174 expression is positively linked to lymph node invasion and tumour–node–metastasis (TNM) stage in ESCC." (PMID 40229851, 2025). "Our results also revealed that high expression of GPR174 in ESCC is associated with tumor metastasis and poor survival outcomes in ESCC patients." (PMID 40229851, 2025). "However, the associations between GPR174 expression level and the age, sex, tumor size, pathological differentiation grade, and T stage of ESCC patients were not statistically significant." (PMID 40229851, 2025). "Collectively, these data suggest that LysoPS, which acts upstream of GPR174, can increase GPR174 expression and promotes tumour metastasis in ESCC." (PMID 40229851, 2025). "Mechanistically, after activation of GPR174 by LysoPS in ESCC, the promotion of tumour metastasis by GPR174 is mediated through the cAMP-PKA-CREB signaling pathway." (PMID 40229851, 2025). "Given the pivotal role of EMT remodeling in tumor metastasis, we next interrogated the impact of GPR174 on EMT biomarker expression (E-cadherin, N-cadherin and vimentin) within hepatic metastasis models." (PMID 40229851, 2025). "Moreover, a correlation was established between LysoPS-mediated tumor metastasis and GPR174 expression in ESCC." (PMID 40229851, 2025). "In a TMA consisting of 98 ESCC tumor samples and 74 matched pairs of ESCC tissues and adjacent normal epithelial tissues, IHC staining was utilized to define the level of the GPR174 protein." (PMID 40229851, 2025).
cancer (1 paper, 2025). A tumor composed of atypical neoplastic, often pleomorphic cells that invade other tissues. "While LysoPS has been involved in the invasion and metastasis of various cancers, LysoPS/GPR174 remains a mystery in terms of its function and mechanisms of action in ESCC progression." (PMID 40229851, 2025). "Nevertheless, no studies have assessed the role of GPR174 in cancer, and we still do not fully understand how LysoPS/GPR174 contributes to ESCC." (PMID 40229851, 2025).
immune disorders (1 paper, 2023). "Given the potential of developing an anti-GPR174 intervention for immune disorders treatments, our structure provides a rational basis for the design of antagonists of LysoPS receptors." (PMID 36823105, 2023).
GPR174 also shares sentences with these, for which no sentence is quoted: autoimmune thyroid disease (3 papers); Addison’s disease (1); autoimmune Addison’s disease (1); bacterial infection (1); esophageal squamous cell carcinoma (1); experimental autoimmune encephalomyelitis (1); lupus (1); myocardial ischemia (1); thyroid-associated ophthalmopathy (1).